LINC01426 (long independently transcribed non-coding RNA 1426)
Synonyms: lincRNA-uc002yug.2
Gene: Long non-coding RNA gene on chromosome 21 (34,745,725 to 34,784,886, forward strand). Ensembl gene ENSG00000234380.
Diseases named in the same sentence as LINC01426 in open-access papers:
LINC01426 is named in the same sentence as 12 diseases in open-access papers, as found by Europe PMC text mining. Sharing a sentence is not in itself a finding about the gene and the disease. The quoted sentences say what the papers report.
glioma (2 papers, 2022 to 2024). A benign or malignant brain and spinal cord tumor that arises from glial cells (astrocytes, oligodendrocytes, ependymal cells). "We further found that the expression of SUMF1, LINC01426, AC061992.2, CARD8-AS1, AC083855.2, AC027307.2, WAKMAR2, and LINC02636, were associated with adverse progression in patients with glioma." (PMID 38460946, 2024). "This study indicates that the ferroptosis process of glioma cells was inhibited after knocking down the expression of LINC01426, which fills the gap in this field." (PMID 36226186, 2022). "The Lasso analysis revealed that the expression of LINC01426, AC061992.2, CARD8-AS1, AC083855.2, AC027307.2, AC026356.1, LYRM4-AS1, WAKMAR2, and LINC02636 were associated with adverse survival time and DSS in patients with glioma." (PMID 38460946, 2024). "Additionally, the expression of LINC01426, AC061992.2, CARD8-AS1, AC083855.2, AC027307.2, WAKMAR2, LINC02636, and SUMF1 were correlated with adverse PFI in patients with glioma." (PMID 38460946, 2024).
glioblastoma (1 paper, 2021). The most malignant astrocytic tumor (WHO grade IV). "In addition, LINC01426 accelerates glioblastoma progression by regulating miR-345-3p/VAMP8 signaling axis." (PMID 34852770, 2021).
lymph node metastasis (1 paper, 2022). "We also analyzed the LINC01426 expression level and LUAD clinical features and found that high LINC01426 expression was associated with tumor diameter; tumor, node, and metastases (TNM) staging; lymph node metastasis (LNM); and overall survival (OS) rate of LUAD patients." (PMID 35266446, 2022).
renal clear cell carcinoma (1 paper, 2022). "LINC01426 was upregulated in renal clear cell carcinoma tissues and its overexpression was correlated with a disappointing prognosis." (PMID 36072969, 2022).
tumor (3 papers, 2020 to 2022). "In vivo experiments were also conducted to validate the role of the LINC01426/SHH axis in LUAD tumor growth." (PMID 33568633, 2021). "Moreover, LINC01426 expression in different tumor TNM stages, LINC01426 expression in LUAD tissues in the I+ II stage was considerably lower than that in the III+IV stage." (PMID 35266446, 2022). "Collectively, highly expressed LINC01426 promotes GBM cell proliferation and tumor growth both in vitro and in vivo." (PMID 32699526, 2020). "Further, qRT-PCR was performed to detect LINC01426 expression levels in 50 pairs of LUAD tumor tissues and normal adjacent tissues, and found significantly higher LINC01426 expression in LUAD tissues than in normal tissues." (PMID 35266446, 2022).
cancer (2 papers, 2020 to 2022). A tumor composed of atypical neoplastic, often pleomorphic cells that invade other tissues. "Interestingly, in our constructed 3-ferroptosis-related lncRNA signature, LINC01426 is an oncogene that has been validated by many cancer researchers." (PMID 36226186, 2022).
LINC01426 also shares sentences with these, for which no sentence is quoted: AIDS (1 paper); leishmaniasis (1); leprosy (1); lung adenocarcinoma (1); malaria (1); tuberculosis (1).